TNF (tumor necrosis factor)
Diseases named in the same sentence as TNF in open-access papers (continued):
Sharing a sentence is not in itself a finding about the gene and the disease.
kidney damage (continued). "Cilastatin decreased the TNFα levels that had previously been increased by gentamicin, thus preventing cell infiltration and exacerbation of kidney damage." (PMID 32899204, 2020). "PPS treatment in this model prevents the progression of nephropathy by decreasing albuminuria, renal macrophage infiltration and TNFα expression; along to improvement of histopathologic changes and renal function." (PMID 31150494, 2019). "Three inflammatory mediators in particular: interleukin 6 (IL-6), tumor necrosis factor α (TNF-α), and C-reactive protein (CRP), when combined in a z-score, are associated with development of retinopathy, nephropathy and cardiovascular disease in diabetics." (PMID 29075511, 2017). "In conclusion, it is possible that JNK and TNF-α commonly contribute to kidney damage, by assembling a positive feedback cycle after CS, leading to increased apoptosis in the renal cortex." (PMID 28701229, 2017). "HMGB1 from injured muscle activates JNK in the kidneys and JNK enhances production of TNF-α, which in turn enhances the production of JNK, resulting in soaring TNF-α level, which contributes to kidney damage." (PMID 28701229, 2017). "The results demonstrated that rhein significantly improved the symptoms of nephropathy through decreasing the production of proinflammatory cytokines, including interleukin 1β, prostaglandin E2, and TNFα." (PMID 26904117, 2016). "Clinically, pentoxifylline has been shown to be beneficial in nephropathies by reducing proteinuria and TNF-α level; however its overall advantage for nephropathies is still a matter of debate." (PMID 25874129, 2015). "Preconditioning with 2 g/kg montelukast significantly attenuated hepatic tissue injury and kidney damage, and decreased plasma interleukin-6 (IL-6) and tumor necrosis factor-α (TNF-α) levels in plasma after intestinal IRI." (PMID 26497763, 2015). "Moreover, TNF-α can induce cell apoptosis and necrosis, increase reactive oxygen species production, and increase albumin filtration, leading to kidney damage." (PMID 40824899, 2025). "Therefore, compounds with anti‐inflammatory properties that target cytokines like TNF‐α and IL‐1β are known to reduce kidney damage due to IRI." (PMID 40025781, 2025). "Cisplatin-induced AKI caused less damage to the kidneys and less production of KIM-1, TNF-α, and Caspase-3, suggesting that a 200 mg/kg combined extract of Zedoary and Turmeric could be used to prevent or lessen kidney damage." (PMID 41509124, 2025). "TNF-α can be toxic to glomerular and mesangial cells, contributing to kidney damage." (PMID 39941397, 2025). "For example, NF-κB is a pleiotropic transcription factor that regulates the expression of many genes involved in the inflammatory response during kidney injury and induces the release of proinflammatory cytokines such as TNF-α, IL-6, and IL-1β, which exacerbate kidney damage." (PMID 40607026, 2025). "They reduced the expressions of TNF-α, Bax, NF-κB, and pathological kidney damage." (PMID 38548778, 2024). "Moreover, EST exhibited an additional ability to decrease the expression of IL-1β and TNF-α, underscoring its potential to suppress the inflammatory response and offering protection against PO-induced kidney damage." (PMID 38540830, 2024). "Therefore, the present study was designed to evaluate the nephroprotective effect of diosmin against cisplatin-induced kidney damage by modulating IL-1β, IL-6, TNFα and renal oxidative damage in rats." (PMID 36770968, 2023). "Immune complexes and necrotic cells can activate innate immune receptors and promote the differentiation of M1 macrophages, which promotes a series of inflammatory responses and leads to kidney damage by secreting proinflammatory cytokines such as TNF-α, IL-1, IL-6, IL-12, and chemokines." (PMID 36059518, 2022). "In addition, damaged mesangial cells release pro-inflammatory factors, such as IL-6, MCP-1, TNF-α and so on, which promotes the inflammatory response, and further aggravates kidney damage." (PMID 35725391, 2022).
kidney damage (continued). "In addition, TNF-α can enhance the generation of free radicals in glomerular mesangial cells, which directly leads to kidney damage." (PMID 36232514, 2022). "In addition, the increased expression of angiopoietin 2, interleukin-6, tumor necrosis factor-α, and endostatin in the blood indicated kidney damage in this model." (PMID 36289909, 2022). "Treatment with ETA partially reduced kidney damage but was very effective to blocking serum TNF-α." (PMID 35647193, 2022). "TNFRSF1B binds to TNF-α and plays a critical role in immune regulation and kidney damage." (PMID 35370692, 2022). "However, pretreatment with kaempferol decreases myeloperoxidase (MPO) activity and the release of proinflammatory cytokines, including TNF-α, thereby decreasing the kidney infiltration of leukocytes and alleviating kidney damage." (PMID 36552226, 2022). "Elevated CCR2 could increase the expression of multiple cytokines and chemokines, such as MCP-1, IL-6 and TNF alpha, and induces mesangial cell proliferation and matrix deposition, and further aggravate kidney damage." (PMID 35725391, 2022). "As observed in the present study, increased NF-κB expression was accompanied by an increase in TNF-α and IL-1β expressions, and a decrease in IL-10, which is anti-inflammatory, suggestive of the involvement of inflammation in the pathogenesis of nephropathy in the untreated diabetic rats." (PMID 34198937, 2021). "Furthermore, the levels of TNF-α and IL-6 increased as nephropathy progressed, with median serum TNF-α levels of 13.49 pg/mL in the normoalbuminuric group, 15.22 pg/mL in the Micro-MA group, and 18.28 pg/mL in the Macro-MA group." (PMID 34663293, 2021). "Studies have suggested that a persistent inflammatory response mediated by pro-inflammatory cytokines such as interleukin 1 beta (IL-1β), interleukin 6 (IL-6) and tumor necrosis factor alpha (TNF-α) contributes to the perpetuation of kidney damage (Furuichi, Kaneko & Wada, 2009)." (PMID 31275747, 2019). "Decreased level of TNF‐α and creatinine level resulted in lowered inflammation and kidney damage." (PMID 30811871, 2019). "Along with proteins of the TNF-α pathway, proteins involved in endothelial cell activation, T-cell activation, and cellular differentiation were also shown to be involved in the progression of nephropathy." (PMID 29445381, 2018). "This study aimed to explore the relationship between HMGB1, JNK, and TNF-α in kidney damage." (PMID 28701229, 2017). "It is intriguing to speculate that some drugs with inhibitory effect on TNF-α activation show imperative benefits for kidney damage." (PMID 28270699, 2017). "In the kidneys with UUO nephropathy, we found that quercetin treatment could diminish macrophage accumulation, TNFα and MCP1 expression." (PMID 27052477, 2016). "In the end, the level of TNF-alphais highly correlated with severity of diabetic retinopathy and with nephropathy.Tear fluid collection may be a useful noninvasive method for the detection of proliferative diabetic retinopathy." (PMID 24259948, 2013). "While the strong association between kidney function and TNF-αR1 levels may be simply attributable to renal clearance of TNF-αR1, TNF-α itself may also play a more complex role in the mediation of kidney damage." (PMID 18681974, 2008). "Indeed, toxin-induced nephropathy in rodents is the result of TNFα-mediated fibrosis." (PMID 40868832, 2025). "Cytokines of the TNF family, TNF SNPs, IL-6 serum levels, and IL6 gene SNPs, as well as macrophage inhibiting factor (MIF) and MIF gene variants, might play a role in favoring kidney damage and have been studied." (PMID 35205271, 2022). "In addition, TNF-α inhibitors can reduce DDP-induced kidney damage and renal dysfunction in mice." (PMID 35355712, 2022).
kidney damage (continued). "Similarly, inflammation was at its lowest levels in CS-exposed groups 7 days post-MI, with plasma TNF-α being below the detectable limit (<5pg/ml) in both sexes, ruling out therefore any potential positive correlation between systemic inflammation and kidney damage." (PMID 32519752, 2020). "In the present study, an elevation of the serum values of IL-1β, IL-6 and TNF-α was observed as the degree of renal damage induced by FA progressed; this is consistent with the histological findings of an increase in inflammatory infiltrates as the degree of kidney damage increased." (PMID 31275747, 2019). "The observed elevation of the soluble TNF receptors supports the hypothesis that high concentrations of sTNFRs are pro-inflammatory by acting as the slow release reservoirs of TNF-α, which may be responsible for the chronic inflammatory state as observed in nephropathy." (PMID 29445381, 2018). "Thus, the suppression on IL-6 and TNF-α could retard or alleviate inflammation and improve nephropathy." (PMID 24886259, 2014). "it kickstarts the production of inflammatory mediators like TNF-α, IL-1β, and MCP-1, which fuel inflammation and worsen kidney damage." (PMID 41368583, 2025). "Ox-LDL has been shown to induce the secretion of tumor necrosis factor-α (TNF-α), interleukin-1β (IL-1β), and MCP-1, leading to increased macrophage infiltration in renal tissue and worsening kidney damage." (PMID 41282283, 2025). "LPS-triggered AKI additionally elevated pro-inflammatory cytokines, such as IL-6, Ccl2, and TNFα, while Inhibiting antioxidant enzymes like GSH, SOD, and GPX, resulting in oxidative stress and kidney damage." (PMID 40225865, 2025). "This reduction in TNF-α levels is crucial, as TNF-α contributes to kidney damage through multiple mechanisms." (PMID 39744177, 2025). "The study found that WIT effectively reduced renal MPO activity and NF-kB, IL-1β, TNF-α, and IL-6 levels in DOX-induced kidney damage." (PMID 40006061, 2025). "In a rat model of rhabdomyolysis-induced acute renal damage, PTX improved the renal function markers and attenuated the pathological signs of kidney damage by dampening the TLR4/NF-κB pathway and the expression of IL-1β and TNF-α." (PMID 38931349, 2024). "Plasma IL-8, IL-10, IL-17, C-C motif chemokine ligand 20 (CCL20), TNF-α and GDF15 correlated with kidney damage assessed as the magnitude of proteinuria." (PMID 39188767, 2024). "Novel kidney injury biomarkers (IL-6, IL-8, TNF-α, NGAL, KIM-1, MMP-9, and IL-18) were used in this investigation to assess kidney damage more accurately." (PMID 38420620, 2024). "Plasma GDF15 and TNF-α and urinary TWEAK and GDF15 most consistently correlated with more active disease or more kidney damage assessed as either higher anti-PLA2R titres, lower eGFR or higher proteinuria." (PMID 39188767, 2024). "Overall, plasma TNF-α and GDF15 and urinary TWEAK and GDF15 most consistently correlated with more active disease and kidney damage assessed as either higher anti-PLA2R titres, lower eGFR or higher proteinuria." (PMID 39188767, 2024). "Relative expression of IL‐6, MCP‐1, IL‐1β, and TNF‐α mRNA were significantly increased in kidney tissue, AND the levels of IL‐1β and p‐p65 were increased in adriamycin‐induced nephropathy rats." (PMID 37382268, 2023). "In rats, the elevated TNF-α, IL-6, and MCP-1 were restored within the normal range in fisetin-treated hyperuricemic nephropathy." (PMID 36552226, 2022). "Recent studies correlated the overexpression of pro-inflammatory (IL-1β, IL-6, TNF-α, and VEGF) and profibrotic genes (ICAM-1 and VCAM-1) with the appearance of nephropathies in diabetic patients." (PMID 36139749, 2022). "In a randomized double-blind placebo-controlled study, the effects of turmeric on TGF- β, IL-8, and TNF-α levels, as well as proteinuria in the urine and serum, were investigated in patients with T2DM nephropathy (n = 20) and a control group (n = 20)." (PMID 34684678, 2021).
kidney damage (continued). "In a nephropathy model, systemic SIRT1 activation suppresses intestinal/renal TNFα expression and ameliorates renal dysfunction." (PMID 33513830, 2021). "Consistently, our previous studies also found an increase of various proinflammatory cytokines, including TNF-α, IL-1β, IL-17, and IL-6, in TCE-hypersensitivity induced kidney damage." (PMID 34393767, 2021). "Taken together, out results suggests an activation of TNF-α/IL6 inflammatory pathways in DPN, similar to those reported in retinopathy and nephropathy." (PMID 33868296, 2021). "We examined the effects of TNF-α inhibition by etanercept (ETN) on kidney inflammation and fibrosis in mice with aristolochic acid (AA) nephropathy as a model of kidney fibrosis." (PMID 34880315, 2021). "The treatment with BA at 10 and 30 mg/kg can restore the imbalance of inflammatory mediators (tumor necrosis factor alpha (TNF-α), interleukin 6 (IL-6), and IL-10) and prevent cecal ligation and puncture-induced kidney damage in mice." (PMID 34721992, 2021). "The levels of IL-11 do not increase.Inhibition of IL-18 cannot significantly prevent kidney damage.CCL5 and IL-1α significantly increase.Inhibition of TNF-α can significantly reduce kidney damage.NLRP3 pathway is less important." (PMID 34149721, 2021). "Our results showed that SCSP treatment significantly upregulated the expression level of apoptotic protein Bcl-2 (p < 0.01) and downregulated Bax, TNF-α, and caspases 3 and 9, thereby reversing the CTX-induced kidney damage." (PMID 32916975, 2020). "The same model demonstrated renal expression of IP-10, IL-10, TNF-α, and TGF-β and a weak correlation with kidney damage." (PMID 26824356, 2016). "Additionally, 5-FU triggered crosstalk between Nrf2 and NF-κB/p38MAPK axis by significantly upregulating p-p38, p-JNK, p-ERK1/2, p-NF-κB, TNF-α, IL-1β, TGF-β, and IL-6, while downregulating Nrf2 and HO-1, resulting in kidney damage." (PMID 40492124, 2025). "Additionally, plasma IL-8, CXCL9, TNF-α and GDF15 showed significant correlation with kidney damage assessed by decreased eGFR." (PMID 39188767, 2024). "The infusion of AngII in rats showed a possible correlation between the activation of the RhoA/ROCK pathway and the expression of Cx43, leading to an increase in pro-inflammatory cytokines, such as the tumor necrosis factor α (TNF-α) and interleukine-1β (IL-1β), and further kidney damage." (PMID 36361888, 2022). "Similarly, apigenin has been demonstrated to reduce IL-6, TNF-α, and IL-1β levels, and increase IL-10 levels in the kidneys or serum in doxorubicin-induced male nephropathy BALB/c mice or in furan-induced nephropathy mice." (PMID 36422572, 2022). "In vivo experiments in mice showed that APS can reverse LPS-induced kidney damage in a concentration-dependent manner (P < 0.05); the concentrations of BUN and Scr were increased (all P < 0.05); similarly, the levels of TNF-α and IL-1β were increased as well (all P < 0.05)." (PMID 33575163, 2021). "High serum and renal levels of TNF-α have been reported in human CKD and experimental kidney disease, including unilateral ureteral obstruction (UUO), ischemia–reperfusion injury (IRI), and cisplatin-induced nephropathy models." (PMID 34880315, 2021). "In the current study, significant increases were observed in serum AAP, LAP, PEPCK, GR, β2-MG, IgA, IgG, LZM, IL-10, and TNF-α concentration in birds exposed to OTA in the diet, indicating that OTA induced kidney damage, oxidative stress, immune response, and inflammation." (PMID 34769489, 2021). "Previous studies have indicated that the levels of TNF-α and IL-6 are significantly elevated in patients with DN, as compared with hyperglycemic patients without nephropathy." (PMID 32076626, 2020). "The serum level of TNF-α in the DM group was significantly higher than controls (p < 0.001); also, the DN group was considerably higher than controls and DM without nephropathy (p < 0.001)." (PMID 32684830, 2020).
kidney damage (continued). "Betaine treatment in rats reduced the TNF‐α level and creatinine level (without no significant decrease), resulting in lowered inflammation and kidney damage." (PMID 30811871, 2019). "The inflammatory cytokines, such as TNF-α and TGF-β1, were involved in kidney damage." (PMID 29569980, 2018). "In our study, higher levels of INF-γ, IL-6, and TNF-α were observed in DM1 patients with CKD in comparison to those without nephropathy, which is in agreement with other studies." (PMID 26770985, 2016). "Previous preclinical and clinical cardiomiopathy and nephropathy studies have shown anti-inflammatory and cytoprotective effects of CB1 antagonists, due to reduction of tumor necrosis factor-alpha (TNF-α) production and inactivation of nuclear factor-kappaB (NF-κB)." (PMID 26078820, 2015). "TNF-α was reported to enhance mRNA expression of Skp2 in a normal rat epithelial kidney cell line (NRK) but not in control cells, which suggests that TNF-α facilitates the induction of Skp2 in nephropathy." (PMID 23255047, 2013). "However, inhibition of TNF-α is not sufficient to avoid the progression of kidney damage to fibrosis." (PMID 35647193, 2022). "Furthermore, we investigated the anti-inflammatory effects and inhibition of necroptosis of Cpd-42, and the results indicated that Cpd-42 reversed the mRNA expression of TNF-α and MCP-1, phosphorylation of p65 and activation of the RIPK3-MLKL signalling pathway in CaOx-induced nephropathy." (PMID 36408256, 2022). "B4 could suppress the expression of IL-6, IL-1β, and NFκB but had a negative effect on TNFα expression, indicating that the anti-inflammatory effects of B4 on adenine-induced kidney damage are related to IL-6 and IL-1β/NFκB signaling." (PMID 31275420, 2019). "Levels of adiponectin were higher in patients with nephropathy (21.84 ± 8.15 vs 14.88 ± 8.27 mg/ml, p = 0.008), but not regarding the presence of retinopathy; neither TNF- α, nor IL-6 and IL-1β showed differences regarding the presence of microvascular disease." (PMID 26382922, 2015). "To elucidate whether short-term PM2.5 exposure could induce kidney damage, we exposed BALB/c mice to PM2.5 intratracheally and measured the biomarkers of kidney injury (KIM-1, cystatin C), oxidative stress (MDA, SOD-1, and HO-1), and inflammatory response (NF-κB, TNF-α)." (PMID 30151074, 2018). "While serum levels of IFN-γ, IL-2, IL-4, and IL-12 did not display a difference between experimental groups (data not shown), expression of IL-5, IL-6, TNF-α, IL-10, CXCL1, and IL-1β was elevated in the NZM2410/J mice displaying signs of severe kidney damage." (PMID 28491039, 2017). "INF-γ, TNF-α, IL6, and IL-10 plasma levels were higher in patients with CKD as compared to those without nephropathy (P = 0.001, P = 0.004, P = 0.016, and P = 0.030, resp)." (PMID 26770985, 2016). "In light of our findings of TAA-induced kidney damage that was protected by metformin, we assessed the kidney tissue levels of phospho-AMPK, total AMPK, MDA, SOD, and TNF-α as well as blood levels of MDA, hsCRP, and TNF-α (data not shown) in all rats at the end of the experiment." (PMID 36985728, 2023). "In addition, it is not clear whether administration of anti-TNF-α, anti-HMGB1 antibodies, and SP600125, a JNK inhibitor, exerts a protective effect against TNF-α induced kidney damage." (PMID 28701229, 2017).